LMAN2L (lectin, mannose binding 2 like)
Description:
May be involved in the regulation of export from the endoplasmic reticulum of a subset of glycoproteins. May function as a regulator of ERGIC-53.
Synonyms: VIPL; DKFZp564L2423; MRD69; MRT52
Tractability: Antibody: UniProt predicts a signal peptide or a membrane-spanning region. PROTAC: ubiquitination databases record sites on it; its protein half-life has been measured.
Gene: Protein-coding gene on chromosome 2 (96,704,993 to 96,740,084, reverse strand). Ensembl gene ENSG00000114988.
Subcellular location: Endoplasmic reticulum membrane; Golgi apparatus membrane
Pathways (Reactome):
Vesicle-mediated transport: COPII-mediated vesicle transport; Cargo concentration in the ER
Gene Ontology:
Molecular function: protein binding; D-mannose binding
Biological process: protein transport; endoplasmic reticulum to Golgi vesicle-mediated transport; protein folding
Cellular component: endoplasmic reticulum membrane; Golgi apparatus; COPII-coated ER to Golgi transport vesicle; endoplasmic reticulum-Golgi intermediate compartment; Golgi membrane; membrane
Genetic constraint (gnomAD): Loss-of-function variants: 21 observed, 33.77 expected, observed/expected ratio (o/e) 0.62, 90% interval 0.44 to 0.9. The upper end of that interval is the gene's LOEUF score, 0.9, which puts it in group 3 of 6, group 1 being the genes least tolerant of losing a copy. Missense variants: 398 observed, 426.29 expected, observed/expected ratio (o/e) 0.93, 90% interval 0.86 to 1.01. Synonymous variants: 169 observed, 167.61 expected, observed/expected ratio (o/e) 1.01, 90% interval 0.89 to 1.14.
Homologues: Orthologues: chimpanzee LMAN2L (99% identical), macaque LMAN2L (99% identical), pig LMAN2L (98% identical), rabbit LMAN2L (97% identical), dog LMAN2L (97% identical), guinea pig LMAN2L (95% identical), mouse Lman2l (91% identical), rat Lman2l (90% identical), tropical clawed frog lman2l (70% identical), zebrafish lman2lb (56% identical), zebrafish lman2la (46% identical), Drosophila melanogaster CG5510 (42% identical), and 1 more. Paralogues in human: LMAN2 (54% identical), LMAN1 (29% identical), LMAN1L (25% identical).
Diseases named in the same sentence as LMAN2L in open-access papers:
LMAN2L is named in the same sentence as 17 diseases in open-access papers, as found by Europe PMC text mining. Sharing a sentence is not in itself a finding about the gene and the disease. The quoted sentences say what the papers report.
bipolar disorder (3 papers, 2021 to 2023). A disorder of the brain that causes unusual shifts in mood, energy, activity levels and the ability to carry out day-to-day tasks. "However, other GWASs reported that bipolar disorder was associated with the gene LMAN2L, encoded near rs6746896 (Chr2)." (PMID 33495595, 2021).
anxiety disorder (1 paper, 2024). A category of psychiatric disorders which are characterized by anxious feelings or fear often accompanied by physical symptoms associated with anxiety. "Genes related to metal binding or metal ion binding (e.g., ATP9B, LMAN2L, TNS3, and TSHZ2) may play a role in the development of anxiety disorders." (PMID 39165506, 2024).
bleeding disorders (1 paper, 2024). "Although ERGIC53 has not been associated with neurological defects but with bleeding disorders, its family member LMAN2L, whose cargoes are not known, is mutated in patients with intellectual disability and epilepsy." (PMID 39115595, 2024).
colorectal cancer (1 paper, 2025). A primary or metastatic malignant neoplasm that affects the colon or rectum. "We discovered that 428 DEGs had a causal association with colorectal cancer through eQTL, of which 38 genes met the FDR statistical standards, and four of these genes (CTSF, PCSK7, LYZ, LMAN2L) also had causal associations through pQTL." (PMID 40381082, 2025). "This study identified CTSF, PCSK7, LYZ, and LMAN2L as critical regulatory genes in colorectal cancer, demonstrating their multifaceted clinical potential in diagnosis, therapeutic intervention, and prognostic evaluation." (PMID 40381082, 2025). "By integrating single-cell data, transcriptomic data, proteomic data and GWAS data for MR analysis, we identified CTSF, PCSK7, LYZ, LMAN2L as potential targets for colorectal cancer." (PMID 40381082, 2025).
emphysema (1 paper, 2025). "Downregulation of LMAN2L gene expression plays an important role in the pathogenesis of COPD with emphysema by weakening airway infection defense and apoptotic cell clearance mechanisms." (PMID 40381082, 2025).
rheumatic disorder (1 paper, 2024). Inflammatory and degenerative diseases of connective tissue structures, such as arthritis. "We found that 11 proteins had a significant association with rheumatic disorders with Bonferroni correction (eTable 13 in Supplement 1), namely, interleukin-27, ICAM5, LMAN2L with JIA; TIMP4 with SSc; and 6 proteins with RA, and 4 proteins with SLE." (PMID 39729320, 2024).
viral infection (1 paper, 2025). "Overall, the LMAN2L gene is involved in protein quality control and transport in the early secretory pathway of cells, playing a crucial role in nervous system development, airway infection defense, tissue damage repair, viral infection, and immune regulation." (PMID 40381082, 2025).
infection (3 papers, 2012 to 2026). The state of being infected such as from the introduction of a foreign agent such as serum, vaccine, antigenic substance or organism. "First, we discovered that HCMV, but not other DNA viruses such as HSV-1 and VACV, induces proteasomal degradation of LMAN2L during the immediate-early stage of infection." (PMID 42149942, 2026). "Of the 11 degraded proteins with roles in protein transport, LMAN2L was the only factor ‘rescued’ from degradation upon infection with a block deletion mutant compared to wild-type infection, highlighting its tractability for further investigation." (PMID 38687323, 2024). "We have also previously demonstrated that LMAN2L was downregulated as early as 4 h post-infection and was rescued upon addition of proteasome inhibitor MG132, but not lysosome inhibitor leupeptin, and that its transcript levels were not downregulated." (PMID 38687323, 2024). "pUS2 is expressed early during infection, consistent with the kinetics of LMAN2L degradation, and localizes to the ER, where it highjacks the ERAD pathway to target cellular proteins for proteasomal degradation in the cytosol." (PMID 38687323, 2024). "Only infection with ΔUS2 rescued LMAN2L expression to mock levels, whereas LMAN2L was still downregulated in the absence of pUS3 and pUS11." (PMID 38687323, 2024). "Given the roles of proteins identified as potential LMAN2L cargo, it would be interesting to determine whether LMAN2L degradation impacts cell migration during infection." (PMID 38687323, 2024). "Like other pUS2 targets, depletion of TRC8 rescued LMAN2L expression during infection." (PMID 38687323, 2024). "Expression of pUS2, pUS3 and pUS11 downregulated LMAN2L compared to mock infection and control RAd." (PMID 38687323, 2024). "Therefore, future studies should also focus on measuring the global impact of LMAN2L downregulation on protein secretion in the context of infection." (PMID 38687323, 2024). "pUS2 expression in the absence of infection is sufficient for the downregulation of its targets, which was also true for LMAN2L where infection with recombinant adenovirus expressing US2 reduced LMAN2L expression." (PMID 38687323, 2024). "Overall, this suggests that pUS2 alone is necessary for LMAN2L degradation during infection and that this phenotype is unlikely to be a result of impaired viral replication." (PMID 38687323, 2024).
tumor (2 papers, 2010 to 2025). "Divergent LYZ and LMAN2L endothelial trends, coupled with cohort-specific CTSF dynamics in T cell subsets, underscore spatial or molecular heterogeneity in tumor microenvironments." (PMID 40381082, 2025).
LMAN2L also shares sentences with these, for which no sentence is quoted: autism spectrum disorder (1 paper); epilepsy (1); glioma (1); hyperprolinemia type 2 (1); Intellectual disability (1); Kabuki syndrome 2 (1); major depression disorder (1); pyridoxine-dependent epilepsy (1).